GTF2E2 (general transcription factor IIE subunit 2)
Diseases named in the same sentence as GTF2E2 in open-access papers:
GTF2E2 is named in the same sentence as 16 diseases in open-access papers, as found by Europe PMC text mining. Sharing a sentence is not in itself a finding about the gene and the disease. The quoted sentences say what the papers report.
lung adenocarcinoma (5 papers, 2021 to 2025). A carcinoma that arises from the lung and is characterized by the presence of malignant glandular epithelial cells. "Previous studies have associated GTF2E2 with poor prognosis in various cancers; for example, knockdown of GTF2E2 inhibits the growth and progression of lung adenocarcinoma via RPS4X in vitro and in vivo." (PMID 40267151, 2025). "GTF2E2 (general transcription factor IIE subunit 2) was found upregulated in lung adenocarcinoma tissue and was negatively associated with patients’ overall survival and the genetic mutations of PRH2 (proline-rich protein HaeIII subfamily 2) were also identified in lung cancer tissue." (PMID 35954157, 2022). "Recent research reported that GTF2E2 plays an oncogenic role in lung adenocarcinoma by interacting with RPS4X." (PMID 34853466, 2022). "Moreover, interactions between GTF2E2 and ribosomal protein S4, X-linked (RPS4X) have been implicated in the onset of lung adenocarcinoma." (PMID 40267151, 2025). "Notably, GTF2E2 was identified as the transcription factor that regulates the most genes which has been reported to exert inhibitory effects on lung adenocarcinoma in the mTOR pathway." (PMID 35749386, 2022).
trichothiodystrophy (4 papers, 2021 to 2025). Trichothiodystrophy or TTD is a heterogeneous group disorders characterized by short, brittle hair with low-sulphur content (due to an abnormal synthesis of the sulfur containing keratins). "GTF2E2 is involved in a range of biological functions, and changes in its expression are linked to various diseases, including trichothiodystrophy, the regulation of stem cell differentiation in spermatogonia and viral replication." (PMID 40267151, 2025). "As a significant component for RNA transcription initiation, GTF2E2 is involved in various biological processes, and its alterations are related to diverse pathological conditions, such as trichothiodystrophy and viral replication." (PMID 34853466, 2022). "As a critical factor for RNA transcription initiation, previous research on GTF2E2 has been focusing on its involvement in trichothiodystrophy." (PMID 33757492, 2021).
glioblastoma (3 papers, 2021 to 2025). The most malignant astrocytic tumor (WHO grade IV). "Previous bioinformatical analysis suggested that GTF2E2 regulates the progression of glioblastoma by upregulating the level of the cell division cycle 20 (CDC20)." (PMID 34853466, 2022).
acute myeloid leukemia (1 paper, 2025). Acute myeloid leukemia (AML) is a group of neoplasms arising from precursor cells committed to the myeloid cell-line differentiation. "For example, in Acute Myeloid Leukemia (AML), GTF2E2 was positively associated with functions like differentiation, metastasis, proliferation, quiescence, inflammation, EMT, hypoxia, and angiogenesis." (PMID 40267151, 2025).
bladder cancers (1 paper, 2025). "However, the mutations were most prevalent in prostate, uterine, and bladder cancers (PRAD, UCEC, and BLCA, respectively), highlighting a potential link between GTF2E2 mutations and tumors of the urinogenital system." (PMID 40267151, 2025).
colon cancer (1 paper, 2017). "To assess their implication we performed small hairpin RNA (shRNA) knockdown of the putative rate-limiting proteins, AP3B1 and GTF2E2, in shRNA transfected HCT116 human colon cancer cell lines followed by western blot." (PMID 29032074, 2017).
glioma (1 paper, 2025). A benign or malignant brain and spinal cord tumor that arises from glial cells (astrocytes, oligodendrocytes, ependymal cells). "Recent findings also highlight the overexpression of GTF2E2 in glioma and suggest a potential link between its expression levels and the prognosis of glioma patients, indicating its involvement in cancer development." (PMID 40267151, 2025).
cancer (6 papers, 2021 to 2025). A tumor composed of atypical neoplastic, often pleomorphic cells that invade other tissues. "Previous research has shown abnormal GTF2E2 expression in several types of cancer, often associated with poor outcomes." (PMID 40267151, 2025). "In the preceding section, we conducted a comprehensive analysis of GTF2E2’s expression level, diagnostic value, prognostic significance, and mutation characteristics across various cancer types." (PMID 40267151, 2025). "In this study, we explored the expression pattern of GTF2E2 and its potential as a diagnostic and prognostic biomarker for various cancers through extensive bioinformatics analysis." (PMID 40267151, 2025). "This consistency between mRNA and protein data underscores the potential diagnostic and therapeutic relevance of GTF2E2 in cancer." (PMID 40267151, 2025). "These genes are notably linked in cancer types where GTF2E2 expression affects patient outcomes, with the exception of BLCA, CHOL, DLBC, PAAD, and UCS." (PMID 40267151, 2025). "To explore the relationship between the gene GTF2E2 and immune responses in cancer, we analyzed its association with various immune cells and regulatory factors across 33 different cancer types." (PMID 40267151, 2025). "In the analysis of the PFI across these cancers, GTF2E2 was associated with an increased risk in ACC, LGG, KICH, KIRC, KIRP, LIHC, MESO and PAAD." (PMID 40267151, 2025). "In the context of cancer, GTF2E2 was found to activate pathways associated with apoptosis, cell cycle regulation, EMT, DDR, and AR signaling." (PMID 40267151, 2025). "Our findings underscore GTF2E2’s multifaceted roles in cancer biology, highlighting its potential as a diagnostic biomarker, prognostic indicator, and immunotherapeutic target across various malignancies." (PMID 40267151, 2025). "GTF2E2 expression was significantly elevated in most cancers compared to normal tissues, with notable diagnostic potential (AUC > 0.7) in 20 cancer types." (PMID 40267151, 2025). "Furthermore, we identified age-related associations with GTF2E2 expression in specific cancer types." (PMID 40267151, 2025). "Employing a multi-pronged approach with tools including R, Cytoscape, TISIDB, cBioPortal, STRING, GSCALite, and CancerSEA, we investigated GTF2E2’s expression patterns, prognostic value, mutational landscape, functional enrichment, and immunological associations across 33 cancer types." (PMID 40267151, 2025). "Functional enrichment analyses highlighted GTF2E2’s involvement in key cancer-related and immunological pathways." (PMID 40267151, 2025). "In summary, we utilized various methods to demonstrate the importance of GTF2E2 across multiple cancer types." (PMID 40267151, 2025). "To further understand GTF2E2’s prognostic value, we conducted survival analyses across various cancers using Kaplan-Meier survival curves, focusing on OS, DSS, and PFI." (PMID 40267151, 2025). "GTF2E2 expression varied across molecular and immune subtypes and correlated with tumor stage and patient age in several cancers." (PMID 40267151, 2025). "In our study, we utilized the cBioPortal tool to examine genetic alterations in the expression of the gene GTF2E2 across a spectrum of cancers, based on data from 32 studies within the TCGA PanCancer Atlas, comprising 10,967 samples." (PMID 40267151, 2025). "We explored the role of the GTF2E2 gene across various cancers using the CancerSEA database to assess its impact at the single-cell level." (PMID 40267151, 2025). "GTF2E2 expression is generally low in normal tissues, yet our analysis using TCGA and GTEx datasets reveals significantly higher levels in most cancer types compared to normal tissues." (PMID 40267151, 2025). "Subsequent analysis showed a significant correlation between the expression of GTF2E2 and these hub genes across various cancers, suggesting their interconnected roles in oncological processes." (PMID 40267151, 2025).
cancer (continued). "High GTF2E2 expression is associated with better outcomes in CESC, SKCM, and THCA, but correlates with worse prognosis in several cancers, including ACC and PAAD, among others." (PMID 40267151, 2025). "Our study used bioinformatics and experimental validation to explore the role of GTF2E2 in different cancers." (PMID 40267151, 2025). "In specific cancer types, such as BRCA, KIRC, LGG, SARC, SKCM, and THCA, GTF2E2 is positively linked with immunostimulators, indicating a potential role in enhancing immune responses." (PMID 40267151, 2025). "Our findings, depicted across, indicate that protein expression of GTF2E2 is substantially higher in 9 types of cancers compared to normal tissues." (PMID 40267151, 2025). "Future research should thoroughly explore GTF2E2 expression across a broad range of cancer subtypes, focusing on specific molecular and immune categories." (PMID 40267151, 2025). "Our findings reveal a consistent increase in GTF2E2 expression with advancing tumor stages across multiple cancer types, suggesting its potential as a prognostic biomarker." (PMID 40267151, 2025). "Based on previous research, we discovered that GTF2E2 expression levels significantly affect OS across 15 different types of cancer." (PMID 40267151, 2025). "Subsequently, we investigated the variation in GTF2E2 expression based on patient age across different cancers." (PMID 40267151, 2025). "GTF2E2 expression varies across different cancer types, which include both molecular and immune-related subtypes." (PMID 40267151, 2025). "Both GTF2A2 and GTF2E2 are known to be involved in the initiation of RNA transcription and are frequently overexpressed in cancer." (PMID 37631095, 2023). "Previous studies have reported that GTF2E2 is expressed aberrantly in several cancers and correlates with poor prognosis." (PMID 34853466, 2022). "Our findings suggest that GTF2E2 may serve as an important biomarker for diagnosis and prediction of prognosis in a variety of cancers." (PMID 40267151, 2025). "These insights suggest a mechanism by which GTF2E2 may contribute to both tumor initiation and progression, emphasizing its potential as a target in cancer therapy." (PMID 40267151, 2025). "There is a lack of more detailed research on the biological function of GTF2E2 in pan-cancer." (PMID 40267151, 2025). "These target genes may include oncogenes and oncogenes, and their altered expression levels may lead to different roles of GTF2E2 in different cancer types." (PMID 40267151, 2025). "Notably, the ROC AUC values exceeded 0.6 in 24 cancer types and 0.7 in 20 types, suggesting a strong link between increased GTF2E2 expression and cancer development." (PMID 40267151, 2025). "Our findings revealed that GTF2E2 was significantly upregulated in UCEC and may serve as a potential diagnostic and prognostic biomarker for this cancer type." (PMID 40267151, 2025). "This study provides a comprehensive examination of GTF2E2’s role across different cancers, exploring its involvement in key signaling pathways, mutation sites, and its association with immune cell infiltration, which were further validated through in vitro experiments." (PMID 40267151, 2025). "We evaluated GTF2E2 mRNA expression in 33 types of cancer, analyzing 18,102 unpaired samples." (PMID 40267151, 2025). "Additionally, a shallow deletion in GTF2E2 mRNA expression was generally prevalent across the studied cancer types, except in LAML and THYM." (PMID 40267151, 2025). "We first examined the immune subtypes of the original 15 cancers and found substantial variations in GTF2E2 expression in seven cancers: PAAD across five subtypes; LGG and LUAD, each in four subtypes; GBM in three subtypes; and KIRC, KIRP, and MESO, each in six subtypes." (PMID 40267151, 2025). "To this end, we assessed GTF2E2 expression across different cancer stages." (PMID 40267151, 2025).
cancer (continued). "These insights suggest that GTF2E2 may act as an independent prognostic marker in various cancers, with its expression levels predicting different clinical outcomes across tumor types." (PMID 40267151, 2025). "Additionally, we delved into the specific cancer types to examine the relationship between GTF2E2 and their functional statuses." (PMID 40267151, 2025). "Recent bioinformatics analyses have shed light on the role of GTF2E2 in cancer progression." (PMID 40267151, 2025). "Our study uses bioinformatics to explore the role of GTF2E2 across different cancers." (PMID 40267151, 2025). "This elevation in GTF2E2 expression suggests its potential value in early cancer diagnosis." (PMID 40267151, 2025). "In exploring the role of GTF2E2, a gene associated with immune regulation, we found that its expression correlates positively with the presence of CD4+ and CD8+ T cells across various cancers." (PMID 40267151, 2025). "To determine whether GTF2E2 signals through RPS4X to mediate cancer cell proliferation, we further knocking down GTF2E2 in RPS4X-OE-A549 cells." (PMID 33757492, 2021). "Some genes always selected by each method were found (COPS7B, DONSON, GTF2E2, HAUS8, PRH2, and ZNF18) with known roles in cancer formation and progression." (PMID 35954157, 2022). "Moreover, the interaction between cancer cells and immune cells within the TME not only facilitates tumor growth but also correlates strongly with increased GTF2E2 expression." (PMID 40267151, 2025). "It is important to note that variations in GTF2E2 expression are observed even in cancers that do not primarily rely on it for predicting survival outcomes." (PMID 40267151, 2025). "Taken together, these findings suggest that GTF2E2 may act as an essential indicator for postoperative recurrence in ESCC, thus providing a promising therapeutic and prediction target for cancer prevention." (PMID 34853466, 2022). "This inconsistency might explain why changes in GTF2E2 expression do not always correlate with survival rates in some cancers." (PMID 40267151, 2025). "In certain cancer subtypes, abnormal levels of GTF2E2 may lead to results that are not reflective of the overall patient population within that subtype." (PMID 40267151, 2025). "No significant age-related differences in GTF2E2 expression were observed in other cancers." (PMID 40267151, 2025). "Similarly, some progressors (CHMP4B, CSTF1, and LSM14B) and suppressors RBPs (ATP5F1A, GTF2E2, RTF1, ELAC2, LRRC47, and MRM3) have never been associated with COAD or READ, but present oncogenic properties in other cancer types." (PMID 37384253, 2023).
tumor (3 papers, 2021 to 2025). "Future research should employ xenograft or genetically engineered mouse models and investigate GTF2E2 expression and prognostic significance in clinical tumor samples." (PMID 40267151, 2025). "Based on the TCGA database, the expression of GTF2E2 was shown to be significantly higher in ESCC tumor samples relative to normal tissues." (PMID 34853466, 2022). "ESCC cells were injected into nude mice subcutaneously to observe the role of GTF2E2 on tumor growth." (PMID 34853466, 2022). "The reduction of FUS expression was observed in the tumor xenografts derived from Eca-109 and KYSE-150 cells with GTF2E2 downregulation, and the opposite trend was found in the tumor xenografts derived from TE-1 cells with GTF2E2 upregulation." (PMID 34853466, 2022). "Through bioinformatical analysis and IHC staining in tumor tissue microarray, we found that GTF2E2 was overexpressed in tumor tissues of ESCC compared with that in adjacent non-tumor tissues." (PMID 34853466, 2022). "Future research confirming this in a larger cohort of animals is warranted to further explore the role of GTF2E2 not only in LUAD but also in other tumor types." (PMID 33757492, 2021). "Based on RNA-sequencing data in TCGA database, the mRNA level of GTF2E2 was found to be significantly higher in tumor samples than in normal tissue (p < 0.001)." (PMID 33757492, 2021). "We also obtained the mRNA sequencing data of 34 stage I LUAD patients who have received lobectomy in our institution and observed the increased GTF2E2 expression in tumor tissues." (PMID 33757492, 2021). "The overexpression of RPS4X in both A549 and H1299 cell lines generated an opposite effect compared with GTF2E2 knockdown, leading to increased tumor cell proliferation and migration as well as tumorigenesis." (PMID 33757492, 2021). "Considering the results from in vitro assays, the GTF2E2 knocking down significantly inhibited the tumor cells’ ability to proliferate and form a tumor in vivo, explaining the disappearance or shrinkage of the tumors in this cohort." (PMID 33757492, 2021). "GTF2E2 is oncogenic in some tumours and protective in others." (PMID 40267151, 2025). "To decipher the mechanism by which GTF2E2 regulates LUAD’s development, using CO-IP and IC-MS/MS analyses, we identified RPS4X, whose potential function in tumor development had been widely reported previously, as an essential factor in GTF2E2-mediated tumor progression." (PMID 33757492, 2021). "Taken together, we inferred that GTF2E2 led to tumor progression via the interaction with RPS4X." (PMID 33757492, 2021). "We found that GTF2E2 knockdown by shRNA significantly inhibited tumor growth in the mouse model: the knockdown of GTF2E2 lead to complete disappearance of the tumor in 6 out of 8 mice and a significant shrinkage in the other two mice, which was consistent with our in vitro results." (PMID 33757492, 2021). "Next, to determine whether GTF2E2 expression had any effect on tumor growth in vivo, we performed a tumor formation assay by subcutaneously injecting GTF2E2-underexpressed A549 cells or control cells into the flanks of nude mice." (PMID 33757492, 2021). "However, the biological functions of GTF2E2 in ESCC tumor progression largely remain unclear." (PMID 34853466, 2022). "To reveal the potential biological function of GTF2E2 in ESCC, we explored its expression level in tumor and adjacent normal tissues through bioinformatical and experimental approaches." (PMID 34853466, 2022). "In the present study, we demonstrate that GTF2E2 is significantly upregulated in ESCC and markedly correlated with tumor recurrence after surgery of ESCC." (PMID 34853466, 2022). "To explore the potential biological function of GTF2E2 in LUAD, we first examined its expression level in tumor and adjacent normal tissues through multiple bioinformatical and experimental approaches." (PMID 33757492, 2021).
tumor (continued). "The reduction of Ki67 expression was observed in the tumor xenografts derived from Eca-109 and KYSE-150 cells with GTF2E2 depleted, and the opposite results were observed in TE-1 cells with GTF2E2 upregulated, suggesting that GTF2E2 played a vital role in ESCC growth." (PMID 34853466, 2022). "We found that GTF2E2 expression was significantly upregulated in advanced tumor tissues of LUAD compared with that in early tumor or adjacent non-tumor tissues." (PMID 33757492, 2021). "Besides, we demonstrated that GTF2E2 knockdown inhibited LUAD cell proliferation, migration, invasion, and promote apoptosis in vitro, as well as attenuated tumor growth in vivo." (PMID 33757492, 2021). "Considering the critical role that mTOR signaling pathway plays in multiple tumor types, this novel discovery prompted us to wonder whether a similar mechanism exists in LUAD when RPS4X is activated by upstream molecules, like GTF2E2." (PMID 33757492, 2021).
GTF2E2 also shares sentences with these, for which no sentence is quoted: esophageal squamous cell carcinoma (2 papers); asthma (1); COVID-19 (1); endometrial cancer (1); lung carcinoma (1); myocarditis (1); Renal Cell Cancer (1).